BCL2 (BCL2 apoptosis regulator)
Diseases named in the same sentence as BCL2 in open-access papers (continued):
Sharing a sentence is not in itself a finding about the gene and the disease.
tumor (continued). "In contrast to the epithelial cells, carboplatin treatment led to increased expression of pro-survival factors (Bcl2, Mcl1, Ier3, Ier5, Hmox1) in stromal cell populations, thus preserving their viability and potentially providing a means of stabilizing and prolonging the anti-tumor response." (PMID 37660083, 2023). "Besides, these nanocarriers mediated endosomal escape of ElF5A2‐siRNA to release it in cytoplasm for downregulation of ElF5A2 as a tumor‐promoting factor to suppress proliferation and invasion of bladder tumor cells and to stimulate apoptosis via Bax upregulation and Bcl‐2 downregulation." (PMID 36684065, 2023). "In addition, it has been found that erastin could increase Bax expression and decrease Bcl-2 expression in tumor cells." (PMID 37268653, 2023). "Moreover, although we chose to knock down the expression levels of CKAP5 protein in this study, advancing this new therapeutic option to the clinic may require choosing a more tumor‐specific target such as Bcl‐2 or Irf‐4." (PMID 37171801, 2023). "In addition, our results showed that CXCL3 overexpression also exerts its role to regulate Bcl-2, Bcl-2/Bax and Cyclin D1 expression that are responsible for apoptosis and cell cycle, the processes upon which tumor cells depend for proliferation, survival, and metastasis." (PMID 38031087, 2023). "It has been also reported that Beclin1 deficiency in breast cells could contribute to tumor formation in a way independent of its role in autophagy and through interaction with Bcl2." (PMID 36760166, 2023). "Importantly, stimulation of T cells through CD3 engagement and co-cultures with HS-5 stromal cells activated primary HC and decreased the pro-apoptotic effect of venetoclax, clearly showing a protective effect of the tumor microenvironment towards BCL-2 inhibition." (PMID 36968995, 2023). "In addition, in vivo experiments showed that this Bcl-2 inhibitor could also induce rapid and complete tumor suppression in multiple xenograft models established using small-cell lung cancer and hematologic cell lines." (PMID 36982637, 2023). "Therefore, the BCL-2/XL inhibitor navitoclax combined with olaparib could substantially inhibit tumor growth in the patient-derived xenograft ES model." (PMID 37894324, 2023). "An evasion of cell death is described for several tumor types due to the disruption of the intrinsic pathway of apoptosis and/or an imbalance of the expression of pro- and anti-apoptotic proteins toward an increase in the amount of anti-apoptotic BCL-2 proteins." (PMID 37210688, 2023). "Numerous studies have linked CR and SB’s ability to inhibit tumor growth in the DEN animal model of cancer to their ability to induce apoptosis by upregulating caspase-3 and Bax and downregulating the anti-apoptotic protein Bcl-2, which in turn encourages apoptosis." (PMID 37627094, 2023). "Since cells of different origins can vary in their dependence on antiapoptotic proteins, precise knowledge of the Bcl-2 interactome could help to predict the response of tumor cells to BH3-mimetics or to design new compounds to activate the intrinsic pathway of apoptosis in cancer cells." (PMID 36899936, 2023). "Interestingly, BCL2 alone is also insufficient to induce full tumor development." (PMID 37457123, 2023). "Downregulation of XIST in our study may have an anti-tumour effect by regulating miRNA-153-3p/BCL2." (PMID 36038831, 2022). "ABT-737 is an antagonist of small molecule Bcl-2, which could induce tumor cell apoptosis without causing damage to normal cells." (PMID 36463199, 2022). "Therefore, BCL2 has both carcinogenic and tumor suppressive effects." (PMID 35814404, 2022). "Another previously identified tumor-suppressing lncRNA related to HNSCC is the nuclear paraspeckle assembly transcript 1 (NEAT1), strongly associated with suppressing cisplatin resistance by modulating several signaling pathways like the Ras-MAPK and the miR-129/Bcl-2 axis in NPC cells." (PMID 35978835, 2022).
tumor (continued). "In addition to tumor cells, the inhibition of Bcl-2 could also modulate Tregs, which was exemplified by pan Bcl-2 inhibitor GX15-070 (GX15)." (PMID 36080223, 2022). "Thus, the downregulation of Bcl-2 may make the tumor cell more sensitive to other antineoplastic drugs." (PMID 35567250, 2022). "However, Bcl-2 as an anti-apoptotic gene is down-regulated in only tumor cells (p ≤ 0.01)." (PMID 35870982, 2022). "In addition, OPE displayed a significant inhibition in tumor growth in a mouse model, which might be related to enhanced cleaved caspase 3 expression and Bax/ Bcl2 ratio." (PMID 35504024, 2022). "We conducted genomic analysis using paired tumor tissue samples at diagnosis and relapse and observed frequent occurrence of mutations in CREBBP and EZH2, which are involved in lymphomagenesis and progression as a chromatin regulator, as well as mutations in BNFRSF14 and BCL2 as previously reported." (PMID 36199784, 2022). "The family includes antiapoptotic (Bcl-2 and Bcl-xL) and proapoptotic (Bax, Bid, Bak, and Bcl-x) members; balancing their interaction ensures proper apoptotic regulation and cell fate in response to fetal development signals, tissue homeostasis, tumor surveillance, and cell stresses." (PMID 35717615, 2022). "Therefore, strategies to inhibit Bcl2 can activate the apoptotic process in tumor cells." (PMID 35725497, 2022). "Finally, downregulation of Bcl-2 in PCa tumours has been found to produce radiosensitivity in vivo." (PMID 36233505, 2022). "The AS1411 aptamer could suppress the homeostasis of MDA-MB-231 and MCF-7 cells, reducing the life-span of Bcl-2 genes in tumor cells, and hinder nucleolin from attaching to the full element of the AU region in the Bcl-2 gene, eventually triggering apoptotic pathway." (PMID 36430951, 2022). "A significant increase in Bcl-2 expression has been found in PCa tumours that progressed following radiotherapy compared to those where radical prostatectomy was used as the primary treatment, demonstrating the potential of elevated Bcl-2 to act as a marker of radioresistance." (PMID 36233505, 2022). "Furthermore, a strong correlation between the expressions of CD20 and CD27 (r= 0.752, p<0.001) and Bcl2 (r= 0.734, p<0.001) was found in tumor areas of long-term survivors, which may reflect a specific subtype of B cells like memory B cells." (PMID 36685537, 2022). "Moreover, virus-mediated overexpression of miR-199 and miR-34a has been found to lead to control of tumor growth by targeting mTOR, c-MET, HIF-1α, and CD44, as well as complete tumor regression by targeting Bcl-2 and SIRT1 in xenograft murine models of HCC, respectively." (PMID 35954176, 2022). "In addition, FJD could significantly downregulate the protein levels of p-PI3K/PI3K, p-AKT/AKT, p-mTOR/mTOR, NF-κB, p38, and Bcl-2 and upregulate the Bax, Cyt-C, and cleaved caspase-3 in OC tumor tissues and cells." (PMID 35281608, 2022). "A rational explanation for these observations is that TRIM16 plays a tumor suppressive role in GC and hindering its expression could result in higher expression levels for these three tumorigenic genes (β-catenin, CyclinD and BCL2)." (PMID 34452557, 2021). "Likewise, conditional Cre-mediated activation of mutant gain-of-function alleles, under the control of the gene endogenous promoter (MEF2B-D83V) or in the context of the permissive ROSA26 locus (BCL2), allowed to investigate their contribution to tumor development in vivo." (PMID 34456919, 2021). "Besides, Nm@MSNs-DOX/SM kills tumor cells through the Bcl-2/Bax/ROS." (PMID 34120620, 2021).
tumor (continued). "Also, bcl-2 (a major regulator of apoptosis and tumor pathogenesis, progression, and resistance to treatment) was overexpressed in HGSC specimen from women with shorter overall survival of >3 years (p = 0.007) in comparison with women with a longer overall survival of >7 years." (PMID 33815656, 2021). "Moreover, chemokines can sustain cancer cell survival by creating an imbalance between proapoptotic and antiapoptotic proteins in tumor cells (e.g., downregulation of Bcl-2 expression or inhibition of caspase-3 and caspase-9 activation), thereby avoiding tumor apoptosis." (PMID 34575965, 2021). "Antiapoptotic bcl-2 increase or positivity supports survival of damaged cells by blocking growth factors that ensure apoptosis (release of cytochrome c) or slowing proliferation so that cell numbers increase over long periods of time, resulting in tumor formation." (PMID 34188682, 2021). "Therefore, the ratio Bax/Bcl-2 is an excellent indicative of apoptosis in tumor cells." (PMID 35300350, 2021). "Moreover, inhibition of autophagy was detected via the accumulation of p62 and LC3, and increased expression levels of cleaved caspase-3 along with the decreased expression of Bcl-xl and Bcl-2 in tumor tissues indicated that apoptosis was significantly induced after combined treatment." (PMID 34771150, 2021). "PIKfyve and CAPN9 showed a significant difference in mutation frequency between EUR and AFR; PIKfyve was related to Ki-67 expression, suggesting that it could promote tumor proliferation, and CAPN9 was related to the expression of Bcl-2, promoting tumor cell apoptosis." (PMID 34950653, 2021). "However, our results also exhibited that other apoptotic signaling pathways, in addition to the mitochondrial Bax/Bcl-2 expression ratio, might be involved in the inhibition to PC-3 cell growth when tumor immunotherapy, such as SCM or MCM, was adopted." (PMID 33807287, 2021). "Thus, tumor suppressors and proapoptotic molecules like BRCA1 or PTEN bind to IP3R to boost Ca2+ ion uptake at MAMs while tumor promoters and anti-apoptotic molecules such as Bcl2 or Bcl-xL repress mitochondrial Ca2+ ion overload by binding to and inhibiting the channel activity." (PMID 34572262, 2021). "In addition, it was found that Ubc9 positively regulates Bcl2, a well-known tumor promoter, indicating that Ubc9 may play a tumor promoter role in breast cancer development." (PMID 33968766, 2021). "Therefore, the ratio of Bax and Bcl-2 proteins present determines the fate of tumor progression." (PMID 33995644, 2021). "Bcl-2 expression is mainly located on the mitochondrial outer membrane, with an N-terminal transmembrane region controlling mitochondrial membrane voltage, which leads to inhibition of tumor cell apoptosis by inhibiting mitochondrial cytokines (i.e., cytochrome C and apoptotic factors) release." (PMID 33924348, 2021). "In addition, the expression of Bcl-2 in tumor tissues decreased after circANXA2 knockdown." (PMID 34992655, 2021). "Although, we only observed a very moderate trend in the reduction in BCL2 expression using qPCR, the ex vivo tumor growth assay of NCH644 GSCs showed that TMZ and calcitriol effectively synergized, which could even result in the complete elimination of some tumors." (PMID 34298790, 2021). "In order to deliver Bcl-2 siRNA and CTND safely and simultaneously to the tumor cells and achieve a synergistic antitumor effect, CTND was linked to the carrier polymer PPF through an ATP-responsive boronate ester and then assembled with Bcl-2 siRNA to form the siRNA/CTND@PPF NP." (PMID 34163720, 2021). "Ki67, Bcl-2, and Bax staining in tumor cells revealed that, by increasing the incubation time, both the expression of Ki67 and the ratio of Bcl-2/Bax decreases in the IS group when compared with the control group, indicating that the IS has a good killing ability on tumor cells." (PMID 32929372, 2020).
tumor (continued). "Cancer cell dependency on specific anti-apoptotic Bcl-2 proteins could be explained by multiple factors, including tissue of origin, impact of the oncogenic lesions that drove tumorigenesis, and/or factors produced by the tumor stroma." (PMID 32455818, 2020). "Additional evidence exists to explain the paradoxical observation that higher Bcl-2 expression corresponds to a better prognosis in some individuals, suggesting a vacant niche filled by higher levels of apoptosis leading to tumorigenesis or dysregulation of proliferation during tumor growth." (PMID 33003477, 2020). "The tumor cells may undergo several molecular mechanisms to suppress apoptosis and acquire resistance to apoptotic agents by the expression of an anti-apoptotic gene such as bcl-2 or by the downregulation of pro-apoptotic gene such as bax." (PMID 32711410, 2020). "Therefore, the miR-129/Bcl-2 axis mediated the SAHA sensitivity in NPC-tolerant tumor in vivo, which might provide a novel therapeutic strategy to overcome HDACi tolerance in NPC cancer." (PMID 32692721, 2020). "Thus, to eliminate CAFs from the radiated tumor microenvironment, Bcl2 inhibitors, including A-1155463 and ABT-199, and existing anticancer drugs can be used, for example, amsacrine, SN38, cisplatin, mitoxantrone, dactinomycin, dinaciclib, UCN-01, bortezomib, and S63845." (PMID 33207781, 2020). "A variety of tumor cells increased the expression of BCL2 family proteins through multiple mechanisms to ensure cell survival and proliferation, including chromosomal translocation, gene amplification, and downregulation/deletion of microRNAs that degrade BCL2 RNA." (PMID 33292251, 2020). "Most anti-cancer drugs could promote tumor cell apoptosis by up-regulating the ratio of Bax/Bcl-2." (PMID 32357169, 2020). "Therefore, in this paper, the effect of GQN on the mitochondrial apoptotic pathway was determined by documenting the expression of the proapoptotic proteins Bax, Cyt-C, and cleaved Caspase 3 and the antiapoptotic protein Bcl-2 in tumor tissue to explain its antihepatocellular carcinoma effect." (PMID 32831873, 2020). "Thus, tumour cells that are resistant to caspase-mediated cell death, including GBMs that overexpress Bcl-2, might be more sensitive to granzyme A. IFNγ has also previously been implicated in the modulation of levels of HLA ligands." (PMID 31319548, 2019). "Moreover, overexpression of Bax and suppression of Bcl-2 illustrates that the mechanism of tumor suppression of Dis might be through induction of apoptosis." (PMID 31295840, 2019). "Moreover, MITF was reported to upregulate the expression of BCL-2 in tumor cells." (PMID 31333673, 2019). "In addition, the ectopic expression of miR-3188 could suppress tumor cell growth both in vitro and in vivo by inhibiting the antiapoptotic regulator BCL2." (PMID 30961650, 2019). "Moreover, mitochondria play an important role in the apoptotic pathway of tumor cells, and the mitochondria-dependent apoptotic pathway could be regulated by pro-apoptotic and anti-apoptotic proteins of the Bcl-2 and caspase families." (PMID 31803052, 2019). "Thus, a Bcl‐XL inhibitor (e.g. A1331852) or dual Bcl‐2/Xl inhibitor (such as ABT263) should be tested with FGFR inhibitors in other FGFR‐dependent tumour models in order to determine the feasibility of a basket trial testing this combination in multiple FGFR‐dependent malignancies." (PMID 30537101, 2019). "Thus, the Bax/Bcl-2 ratio can affect tumor progression and aggressiveness." (PMID 31861952, 2019). "Therefore, we suggest that reduction in tumor size and weight of Dis treated mice could be as a result of apoptosis via activation of Bax and inhibition of Bcl-2 proteins, respectively." (PMID 31295840, 2019).
tumor (continued). "Therefore, the anti-tumour mechanism of drug-drug combination is to induce apoptosis through up-regulating the activity of caspase-3 and caspase-9 by inhibiting the activity of bcl-2." (PMID 30872765, 2019). "Additionally, the Bax/Bcl-2 ratio is statistically correlated with age and tumor location." (PMID 31340610, 2019). "Interestingly, in the tumors of both groups of patients, the autophagy markers P62 and LC3, the anti-apoptotic BCL-2, and the proliferation marker ki-67 were increased compared to non-tumor specimens, while those of the inhibitor of cell proliferation CDKN1A were reduced." (PMID 29371906, 2018). "CHB-II-F may be down-regulating the expression of Bcl-2 and up-regulating the expression of Bax, while activating both caspase-3 and caspase-9, fixing tumor cells in G0-G1 transition, increasing the rate of apoptosis of rumor cells and stimulating cells to initiate the process of apoptosis." (PMID 30670974, 2018). "The two drugs effectively controlled the tumor growth by blocking the β2-AR, and then consequently suppressing the expression of p-Akt, p-mTOR, Bcl-2, cyclin D1, HK2 and GLUT1, which indicated that propranolol could enhance the efficacy of vemurafenib, a member of TKIs." (PMID 29416656, 2018). "Thus, NEAT1 could regulate the BCL-2-related apoptosis pathway and cyclin D1-related pathway to promote tumor growth of OS cells." (PMID 29654165, 2018). "Indeed, Enza treatment induces BCL-2 in LNCaP, as well as primary patient tumor-derived PCa cells." (PMID 30190514, 2018). "Interestingly, loss of Bcl2-modifying factor did not potentiate Rag-mediated tumor development, as did loss of BIM, even though the proteins are both pro-apoptotic members of the BCL-2 family." (PMID 28692033, 2017). "In conclusion, our meta-analysis suggests a role BCL-2 promoter polymorphisms in cancer susceptibility and prognosis, rs2279115 but not rs1801018 may be a tumor marker for cancer therapy in Asia." (PMID 28445963, 2017). "We speculate that DMDD inhibits cytokine production in the tumor cells in mice, which leads to deactivation of NF-κB pathway, and consequently inhibits the expression of many anti-apoptosis and metastasis-promoting genes, such as Bcl-2 and MMPs." (PMID 28751740, 2017). "In addition, we found the expression of BCL-2 upregulated in rmIL-17 treated tumor bearing mice." (PMID 28002798, 2017). "Attributed to the high ability to bind and stabilize G-qudruplex DNA, phenanthroline derivatives exhibit effectively in inducing apoptosis of various tumor cells, and it’s possible that this kind of compounds may also inhibit the growth of tumor cells through interacting with bcl-2 G-quatruplex DNA." (PMID 28531122, 2017). "However, it is unclear whether ABT-199 would affect tumor microenvironment in a Bcl-2-dependent manner." (PMID 28637496, 2017).